ILDR1 (immunoglobulin like domain containing receptor 1)
Description:
Maintains epithelial barrier function by recruiting MARVELD2/tricellulin to tricellular tight junctions (tTJs). Crucial for normal hearing by maintaining the structural and functional integrity of tTJs, which are critical for the survival of auditory neurosensory HCs. Mediates fatty acids and lipoproteins-stimulated CCK/cholecystokinin secretion in the small intestine. In the inner ear, may regulate alternative pre-mRNA splicing via binding to TRA2A, TRA2B and SRSF1 (By similarity). (Microbial infection) Promotes influenza virus infection by inhibiting viral nucleoprotein NP binding to PLSCR1 and thereby PLSCR1-mediated antiviral activity.
Synonyms: MGC50831; DFNB42; ILDR1alpha; ILDR1alpha'; ILDR1beta
Tractability: Antibody: UniProt places it where antibodies can reach, with high confidence; its Gene Ontology location is reachable by antibodies, with high confidence; UniProt predicts a signal peptide or a membrane-spanning region.
Gene: Protein-coding gene on chromosome 3 (121,987,323 to 122,022,274, reverse strand). Ensembl gene ENSG00000145103.
Subcellular location: Cell membrane; Cell junction, tight junction; Cytoplasm; Cytoplasm, cytosol (Isoform 5)
Gene Ontology:
Molecular function: identical protein binding; protein binding; high-density lipoprotein particle receptor activity
Biological process: epithelial structure maintenance; positive regulation of peptide hormone secretion; protein localization to tricellular tight junction; regulation of RNA splicing; response to fatty acid; tricellular tight junction assembly; vesicle-mediated transport
Cellular component: cytoplasm; plasma membrane; protein-containing complex; tight junction; tricellular tight junction; bicellular tight junction; cytosol
Genetic constraint (gnomAD): Loss-of-function variants: 54 observed, 61.4 expected, observed/expected ratio (o/e) 0.88, 90% interval 0.71 to 1.1. The upper end of that interval is the gene's LOEUF score, 1.1, which puts it in group 4 of 6, group 1 being the genes least tolerant of losing a copy. Missense variants: 719 observed, 723.87 expected, observed/expected ratio (o/e) 0.99, 90% interval 0.93 to 1.06. Synonymous variants: 278 observed, 286.02 expected, observed/expected ratio (o/e) 0.97, 90% interval 0.88 to 1.07.
Gene-disease validity (ClinGen):
ClinGen rates the evidence that ILDR1 causes each of these diseases.
nonsyndromic genetic hearing loss (autosomal recessive): Definitive. A disease characterized by hearing loss that is not part of a larger syndrome.
Homologues: Orthologues: chimpanzee ILDR1 (99% identical), macaque ILDR1 (97% identical), rabbit ILDR1 (81% identical), guinea pig ILDR1 (80% identical), mouse Ildr1 (79% identical), rat Ildr1 (78% identical), dog ILDR1 (76% identical), pig ILDR1 (71% identical), zebrafish ildr1b (41% identical), zebrafish ildr1a (37% identical). Paralogues in human: ILDR2 (26% identical), LSR (25% identical).